EGFR (epidermal growth factor receptor)
Diseases named in the same sentence as EGFR in open-access papers (continued):
Sharing a sentence is not in itself a finding about the gene and the disease.
pancreatic cancer (continued). "The targets of CAR-T cell clinical trials in the treatment of pancreatic cancer patients include EGFR, HER2, CD133, and mesothelin." (PMID 41417221, 2025). "Combined detection of the exosomal membrane proteins EGFR and HER2 improves the diagnostic sensitivity of pancreatic cancer (85%) and is particularly effective in CA19-9-negative patients." (PMID 40612948, 2025). "The strong association found between AQP5 and EGFR, and the associations between AQP3/AQP9 and c-Jun in pancreatic tumor tissues highlight the implications of AQPs in the settings of tumorigenesis." (PMID 40305202, 2025). "The overexpression of EGFR on the surface of pancreatic neoplastic cells has been observed in 30–89% of patients with pancreatic cancer." (PMID 40282495, 2025). "Increasing evidence has demonstrated that the suppression of the EGFR signaling pathway leads to reduced pancreatic cancer growth, being therefore, recognized as a powerful anticancer approach." (PMID 40708975, 2025). "Overexpression of the epidermal growth factor receptor (EGFR) has been implicated in the development of various human cancers, including lungs, breast, and pancreatic cancer." (PMID 40141117, 2025). "It is noteworthy that the effect of the tested nanomaterials on the total level of EGFR and its activation was much higher in mouse pancreatic cancer than in the case of AsPC-1." (PMID 39916650, 2025). "It is an EGFR tyrosine kinase inhibitor used to treat certain small cell lung cancers or advanced metastatic pancreatic cancers." (PMID 40539058, 2025). "In the context of the high-glucose microenvironment characteristic of tumors, curcumin counteracts EGF-induced activation of the EGFR/ERK/Akt signaling pathway in pancreatic cancer cells, thereby inhibiting cell proliferation and invasion." (PMID 41515171, 2025). "CAR-T therapy targeting EGFR, an important target in metastatic pancreatic cancer, has demonstrated some clinical efficacy." (PMID 40969260, 2025). "The ML analysis revealed that the combination of GPC1 and EGFR, with low correlation, significantly improved the prediction accuracy for pancreatic cancer screening." (PMID 40598854, 2025). "In this study, nimotuzumab, an EGFR inhibitor approved for pancreatic cancer therapy, will be utilized." (PMID 40689200, 2025). "The results of in vitro experiments revealed that rhein and erlotinib, when used in combination, inhibited the phosphorylation of STAT3 and EGFR in pancreatic cancer cell lines, thereby inhibiting the proliferation of pancreatic cancer cells." (PMID 40535810, 2025). "In pancreatic cancer cells, azithromycin was shown to enhance the cytotoxicity of the EGFR inhibitor gefitinib through autophagy inhibition." (PMID 40847193, 2025). "Among these, epidermal growth factor receptor (EGFR) inhibitors like erlotinib have shown promise for treating cancers such as non-small cell lung and pancreatic carcinomas." (PMID 40807472, 2025). "In clinical trials using a combination of gemcitabine and the EGFR inhibitor erlotinib, survival rates improved in patients with pancreatic cancer." (PMID 39744013, 2024). "In pancreatic cancer, mutated KRAS upregulates endogenous EGFR expression, and hyperactivation results in a transformation from acinar to ductal metaplasia." (PMID 38396679, 2024). "Overexpression of EGFR or the ability of mutant versions to control downstream signaling is observed in pancreatic cancer." (PMID 39239563, 2024). "We report that in cultured human and mouse pancreatic cancer cells, exogenous GH treatment partially rescues tumor cells from the cytotoxic effects of chemotherapies—gemcitabine, doxorubicin, and the EGFR-inhibitor, erlotinib." (PMID 39000545, 2024). "Curcumin has the ability to inhibit not only the protein phosphorylation of STAT1 and STAT3 but also the EGFR and Notch‐1 signaling processes, all of which play important roles in the progression of pancreatic cancer." (PMID 38690008, 2024).
pancreatic cancer (continued). "In pancreas cancer, for example, cell lines that have mesenchymal features tend to be resistant to inhibition of the epidermal growth factor receptor (EGFR) but exhibit sensitivity to gemcitabine chemotherapy." (PMID 37832945, 2024). "In our study, we demonstrate that anti-EGFR is effective in PC patients with higher expression of ARNTL2 as demonstrated in our studies using various pancreatic cancer cell lines and PC-PDX models." (PMID 38459558, 2024). "Overexpressed in 57–95% of pancreatic cancer patients, EGFR activation frequently occurs concurrently with cancer progression and metastasis." (PMID 39770538, 2024). "For example, Goutam Mondal and co-workers prepared an epidermal growth factor receptor (EGFR)-targeted gemcitabine (GEM)-conjugated polymeric mixed micelles GE11-PEG-PCD/mPEG-b-PCC-g-GEM-g-DC to treat pancreatic cancer." (PMID 38474185, 2024). "The study demonstrated that epimedium extract inhibits the expression and phosphorylation of AKT1 and EGFR in the pancreatic cancer cell line PANC-1." (PMID 39011503, 2024). "EPLIN was also found to have an impact on pancreatic cancer cells response to chemotherapeutic and EGFR/HER2 targeted therapeutic agents, namely gemcitabine, fluorouracil (5FU) and neratinib (Nerlynx)." (PMID 39730634, 2024). "Pancreatic cancer is characterized by the accumulation of numerous genetic alterations, with early occurrences of KRAS mutations and EGFR gene amplification occurring during disease progression." (PMID 39087024, 2024). "Glutamine deprivation in some pancreatic cancer cell lines induced macropinocytosis via the EGFR signalling pathway." (PMID 39420093, 2024). "This gene is associated with a psoriasis-like skin phenotype and induces the EMT in pancreatic cancer cells through EGFR/ERK/NF-kB." (PMID 38392212, 2024). "Distinct from our work, Mucciolo and colleagues reported that in pancreatic cancer, stromal EGFR activated by AREG is involved in the acquisition of pro-tumorigenic properties that favor cancer cells via myofibroblast activation." (PMID 39262776, 2024). "In vitro data have shown that ibrutinib radiosensitizes pancreatic cancer cells through EGFR and PI3K/Akt pathway inhibition." (PMID 39659349, 2024). "Preclinical evaluation in lung, colorectal, and pancreatic cancer cell line xenografts demonstrated that BL-B01D1 improved cytotoxicity over EGFR or HER3 monospecific ADCs." (PMID 39065587, 2024). "EGFR inhibitors are often used as monotherapies or in combination with radiotherapy for the treatment of solid tumors, such as lung, colorectal, and pancreatic cancers." (PMID 39204145, 2024). "Recently, a liposomal irinotecan combined with an anti-EGFR/FAP bispecific antibody demonstrated improved efficacy in pancreatic cancer xenograft models." (PMID 39033209, 2024). "The STAT1, STAT3, EGFR, and Notch‐1 signaling pathways can be blocked to prevent the development of pancreatic cancer." (PMID 38690008, 2024). "ALT significantly inhibited constitutively activated STAT3 in pancreatic cancer cells while having minimal effect on the EGFR pathway." (PMID 38397437, 2024). "A preclinical study has reported successful outcomes with antibody therapy targeting galectin-3 in pancreatic cancers via EGFR, indicating that galectin-3 blockade reduced tumor cell migration, adhesion, and invasion." (PMID 39451592, 2024). "Western blotting evaluated the p-EGFR/KRAS/p-ERK1/2 signaling pathway in pancreatic cancer cells (PANC-1 and MIA PACA-2) under individual and combined CSI and erlotinib treatments." (PMID 39770538, 2024). "Patients with KRAS wild‐type disease and early‐onset pancreatic cancer (EOPC) harbored actionable mutations including BRAF, EGFR, ERBB2, and MAP2K1/2.PGVs in PALB2, BRCA2, and ATM were associated with high PDAC risk in the Chinese population." (PMID 36999792, 2023).
pancreatic cancer (continued). "Nevertheless, there are evidence that pancreatic cancer cells with EGFR high expression were sensitive to nimotuzumab treatment in vivo and results for EGFR-overexpression just reach statistical significance in the German clinical trial." (PMID 37152586, 2023). "Through this work, an EGFR-targeted bioluminescent–dendrimer complex enabled the straightforward identification and imaging of pancreatic cancer cells in vivo in preclinical models." (PMID 37514162, 2023). "Patients with KRAS wild‐type disease and early‐onset pancreatic cancer (EOPC) harbored actionable mutations including BRAF, EGFR, ERBB2, and MAP2K1/2." (PMID 36999792, 2023). "The epidermal growth factor receptor (EGFR) is overexpressed in pancreatic tumor cells where it is believed to promote cell survival, proliferation, tissue invasion, and metastasis formation while inhibiting apoptosis." (PMID 37152586, 2023). "A reduction in EGFR expression was recorded in metastatic lesions of pancreatic cancer after CAR-T therapy." (PMID 37998753, 2023). "ROS can also promote the pancreatic cancer formation by activating NF-κB and upregulating EGFR proliferative signaling via protein kinase D1." (PMID 37528424, 2023). "The expressions of EGFR, HER2, and VEGFR were evaluated in mice pancreatic tumor tissues using EGFR, HER2, and VEGFR staining." (PMID 37179357, 2023). "Studies have shown that EGFR is overexpressed in as many as 89–95% of pancreatic cancer cases, making it a good candidate for PDAC detection." (PMID 37514162, 2023). "The results revealed that Gal-3 influenced the cellular distribution of MUC1 and EGFR in pancreatic cancer cells." (PMID 37915694, 2023). "Nimotuzumab exerts its antitumor effect (mainly antiproliferative, proapoptotic, and antiangiogenic) by blocking the epidermal growth factor receptor overexpressing between 30 and 95% in pancreatic tumors cells." (PMID 37152586, 2023). "Research shows that epidermal growth factor receptor (EGFR) and Human Epidermal Growth Factor Receptor 2 are highly expressed in pancreatic cancer patients." (PMID 38012210, 2023). "In a cirrhotic animal model, pancreatic tumor cells, and the EGFR-mediated signaling pathway, quercetin, and quercetin 3-O-glucoside, suppress EGFR expression." (PMID 36768973, 2023). "EGFR is overexpressed in 30–89% of pancreatic cancer, and its role in predicting prognosis remains controversial." (PMID 37179357, 2023). "Most pancreatic cancers overexpress epidermal growth factor receptor (EGFR), a transmembrane receptor tyrosine kinase." (PMID 34844535, 2023). "Our findings indicate that high glucose levels activate EGFR and increase the stability of PD-L1 mRNA, resulting in up-regulated expression of PD-L1 in pancreatic cancer cells." (PMID 37434177, 2023). "KEGG enrichment analysis of pancreatic adenocarcinoma (PAAD) samples from TCGA showed that in pancreatic tumors with diabetes, the terms of EGFR downstream pathways, including JAK-STAT, RAS, and PI3K-Akt, were enriched." (PMID 37434177, 2023). "Our results revealed that a high dose of glucose enhanced the stability of the PD-L1 mRNA in pancreatic tumor cells by downregulating PTRH1 through RAS signaling pathway activation following epidermal growth factor receptor (EGFR) stimulation." (PMID 37434177, 2023). "Among the kinases, EGFR kinase is a promising target due to the overexpression of EGFR in pancreatic cancers; in particular, a treatment strategy mediated by nanoparticles targeting the EGFR ligand has been reported for pancreatic cancers." (PMID 37371811, 2023). "Epidermal growth factor receptor (EGFR) inhibitors are a class of drugs that are used to treat several common malignancies, including breast, colon, lung, and pancreatic cancer." (PMID 36768973, 2023).
pancreatic cancer (continued). "Taken together, these findings suggest NSD3 expression influences the proliferation of pancreatic cancer cells, influences global methylation patterns in the genome of cells, and mediates downstream genes relevant to ERBB and EGFR/ERK signaling." (PMID 37062069, 2023). "The driver mutations in the ctDNA of breast, colorectal, lung, and pancreatic cancers for the KRAS, PIK3CA, EGFR, and HER2 genes have been extensively studied by ddPCR assays." (PMID 37593116, 2023). "In human pancreatic cancer, low expression of Cbl conferred chemoresistance via stress-induced EGFR activation." (PMID 36694209, 2023). "This ADC contained the MMAE payload and was able to overcome EGFR mAb-resistance associated with KRAS mutation, which is present in almost all pancreatic cancers." (PMID 37880707, 2023). "Monensin (MON) targets the EGFR signaling pathway, inhibiting cell proliferation and growth in chemotherapy-resistant pancreatic cancer cells." (PMID 37895063, 2023). "Therapeutically, deprivation of RASON sensitizes KRAS mutant pancreatic cancer cells and patient-derived organoids to EGFR inhibitors." (PMID 36241718, 2023). "The therapeutic potential of our findings was confirmed by the sensitization of pancreatic cancer to EGFR inhibitors upon RASON depletion in PDO models." (PMID 36241718, 2023). "EGFR has been shown to be overexpressed in 30–90% of pancreatic cancer and drives pro-survival and anti-apoptotic pathways, thus making it a suitable target for cancer therapy." (PMID 37880707, 2023). "We choose cetuximab for 64Cu-labeling since the overexpression of EGFR has been observed in up to 90% of pancreatic cancers." (PMID 37895812, 2023). "EGFR is a transmembrane protein closely related to multiple pathological processes such as the proliferation, invasion, and metastasis of pancreatic cancer cells." (PMID 35449823, 2022). "We first developed dual-targeting (anti-EGFR and anti-FAP) irinotecan liposomes for both pancreatic cancer cells and tumor-associated fibroblasts." (PMID 35745775, 2022). "Similar to other gastrointestinal tumors, overexpression of EGFR is reported in more than 60% of pancreatic cancers and 30–60% of cholangiocarcinoma patients based on immunohistochemical analysis." (PMID 35453596, 2022). "Previously, we developed a method to identify pancreatic tumor lesions ≥3 mm using positron emission tomography (PET) with an intraperitoneally administered 64Cu-labeled anti-epidermal growth factor receptor (EGFR) antibody (64Cu-NCAB001 ipPET)." (PMID 36145676, 2022). "Several preclinical studies using pancreatic cancer xenograft in nude mice have supported the strategy to disrupt EGFR-mediated signalling with cetuximab, a monoclonal chimeric IgG1 that targets the receptor protein expressed on the cell surface." (PMID 35892707, 2022). "In pancreatic cancer, Ibrutinib inhibited tumor development by decreasing the phosphorylation of EGFR and reversed the upregulation of p-AKT and downstream genes induced by radiation." (PMID 36145624, 2022). "The aim of this article is to analyze the tissue expression of EGFR, Beta catenin, cyclin D1, CDK4, and ErbB2 in pancreatic cancer in order to find their association with the mortality and survival of patients with this tumor." (PMID 35448172, 2022). "EGFR antagonists such as erlotinib, an EGFR inhibitor used in the treatment of lung and pancreatic cancers, are successful in inhibiting growth of these tumors even though resistance eventually develops." (PMID 36228719, 2022). "Epidermal growth factor receptor (EGFR or ErbB1) is one of the best-characterized markers in pancreatic cancer." (PMID 35448172, 2022). "For that, PLGA NPs were co-loaded with Erlotinib (ERL), an EGFR inhibitor and one of the first-generation approved for lung and pancreatic cancer treatment." (PMID 36559223, 2022).
pancreatic cancer (continued). "Gupta and colleagues constructed a Gem encapsulated nanoplatform against pancreatic cancer through covalent binding to EGFR antibodies, presenting higher cytotoxicity of the designed nanoplatform for EGFR-overexpressing pancreatic cell lines." (PMID 36096856, 2022). "The efficacy of these nanoparticles was studied in many EGFR-positive cell lines of lung, colon, and pancreatic cancers." (PMID 36559202, 2022). "Another study found that the gene expression of KRAS and EGFR pathway signaling molecules changed significantly after IRE treatment on pancreatic tumors." (PMID 36081554, 2022). "Another example is epidermal growth factor receptor (EGFR), which is highly expressed in pancreatic cancer (PC)." (PMID 36559223, 2022). "In pancreatic cancer, Hedgehog and EGFR have synergistic effects on ERK and AKT phosphorylation, hence on cell proliferation, survival, and chemoresistance." (PMID 35154464, 2022). "According to previous research, rhein can sensitize human pancreatic cancer cells to EGFR inhibitors by inhibiting the STAT3 pathway." (PMID 36091816, 2022). "Another study showed that concurrent blockade of IGF1R and its EGFR/Her-2 simultaneously inhibited the pancreatic tumor growth and the stimulation of IRS-1, Akt, and MAPK phosphorylation." (PMID 36556296, 2022). "Although oncogenic KRAS has long been considered to be constitutively active, and thus independent of upstream signals, a requirement for ADAM17 and ERBB1/EGFR in KRAS-induced pancreatic cancer has challenged this idea." (PMID 35971826, 2022). "Of the examined antibodies, those for EGFR and TfR showed relatively high binding to the pancreatic cancer cells used in this study, compared with those for HER2, HER3, EpCAM, LAT1, and CD98." (PMID 35628616, 2022). "When compared to the control group, the protein and gene expression of PDGFR and EGFR was significantly lower in pancreatic cancer cells overexpressing MiR-4723, while it was significantly higher in cells overexpressing CAV2 or Wnt7A." (PMID 35517414, 2022). "Previous studies revealed that CALR enhanced EGF-induced EMT in pancreatic cancer cells via Integrin/EGFR-ERK/MAPK signaling pathway and repressed E-cadherin expression via Snail (SNAI1)/Slug in Madin-Darby canine kidney cells or mouse embryonic stem cells." (PMID 35641480, 2022). "Cetuximab has a high binding affinity for EGFR, which is reportedly overexpressed in >90% of pancreatic cancers." (PMID 35628616, 2022). "In a phase I trial, EGFR-targeting CAR T cells were investigated in 16 patients with metastatic pancreatic cancer whose cells were EGFR-positive by immunohistochemistry (>50%)." (PMID 36291891, 2022). "BxPC3/EGFR pancreatic tumor cells were cultured with LipoIRI or BS−LipoIRI for 3 h to evaluate the cell viability by MTT assay." (PMID 35745775, 2022). "A 2021 study used EGFR-targeting CAR-T cells in co-cultures with either PCTS derived either from a BxPC3 EGFR-expressing pancreatic cancer PDX model or from PCTS derived from NSCLC and ccRC." (PMID 35466279, 2022). "Pancreatic cancer triggers the polarization of TAM M2 by secreting REG4 through the EGFR/AKT/CREB pathway." (PMID 36466812, 2022). "Molecular targets, such as human epidermal growth factor receptor type 1 (HER1/EGFR), which are overexpressed in many pancreatic cancers have also been targeted clinically with mixed outcomes." (PMID 35720978, 2022). "Prominently, the EGFR-KRAS pathway appears to provide a potential target in pancreatic cancer, leading to a plethora of altered cell processes and linking with the activation of additional molecular pathways." (PMID 35448172, 2022). "EGFR is overexpressed in 90% of pancreatic tumors, and EGFR-targeting drugs have become a hotspot in recent years." (PMID 35637953, 2022).